ECHS1 (enoyl-CoA hydratase, short chain 1)
Description:
Converts unsaturated trans-2-enoyl-CoA species ((2E)-enoyl-CoA) to the corresponding (3S)-3hydroxyacyl-CoA species through addition of a water molecule to the double bond. Catalyzes the hydration of medium- and short-chained fatty enoyl-CoA thioesters from 4 carbons long (C4) up to C16. Has high substrate specificity for crotonyl-CoA ((2E)-butenoyl-CoA) and moderate specificity for acryloyl-CoA, 3-methylcrotonyl-CoA (3-methyl-(2E)-butenoyl-CoA) and methacrylyl-CoA ((2E)-2-methylpropenoyl-CoA). Can bind tiglyl-CoA (2-methylcrotonoyl-CoA), but hydrates only a small amount of this substrate. Plays a key role in the beta-oxidation spiral of short- and medium-chain fatty acid oxidation. At a lower rate than the hydratase reaction, catalyzes the isomerase reaction of trans-3-enoyl-CoA species (such as (3E)-hexenoyl-CoA) to trans-2-enoyl-CoA species (such as (2E)- hexenoyl-CoA), which are subsequently hydrated to 3(S)-3-hydroxyacyl-CoA species (such as (3S)-hydroxyhexanoyl-CoA) (By similarity).
Synonyms: mECH; mECH1; SCEH; ECHS1D
Tractability: Small molecule: a structure with a bound ligand is known; it has a high-quality binding pocket. PROTAC: ubiquitination databases record sites on it; its protein half-life has been measured; a small molecule that binds it is known.
Target class: Enzyme; Lyase
Gene: Protein-coding gene on chromosome 10 (133,362,472 to 133,373,714, reverse strand). Ensembl gene ENSG00000127884.
Subcellular location: Mitochondrion matrix
Subcellular location (Human Protein Atlas): Mitochondria
Pathways (Reactome):
Metabolism: Beta oxidation of butanoyl-CoA to acetyl-CoA; Beta oxidation of decanoyl-CoA to octanoyl-CoA-CoA; Beta oxidation of hexanoyl-CoA to butanoyl-CoA; Beta oxidation of lauroyl-CoA to decanoyl-CoA-CoA; Beta oxidation of octanoyl-CoA to hexanoyl-CoA; Branched-chain amino acid catabolism
Disease: Mitochondrial short-chain enoyl-CoA hydratase deficiency 1
Gene Ontology:
Molecular function: 3-hydroxypropionyl-CoA dehydratase activity; enoyl-CoA hydratase activity; protein binding; (2E)-butenoyl-CoA hydratase activity; 3-hydroxyacyl-CoA dehydratase activity; catalytic activity; delta(3)-delta(2)-enoyl-CoA isomerase activity
Biological process: fatty acid beta-oxidation; L-lysine catabolic process; L-valine catabolic process; branched-chain amino acid catabolic process; L-amino acid catabolic process
Cellular component: mitochondrial matrix; mitochondrion
Genetic constraint (gnomAD): Loss-of-function variants: 16 observed, 26.79 expected, observed/expected ratio (o/e) 0.6, 90% interval 0.4 to 0.91. The upper end of that interval is the gene's LOEUF score, 0.91, which puts it in group 3 of 6, group 1 being the genes least tolerant of losing a copy. Missense variants: 274 observed, 308.03 expected, observed/expected ratio (o/e) 0.89, 90% interval 0.81 to 0.98. Synonymous variants: 113 observed, 117.88 expected, observed/expected ratio (o/e) 0.96, 90% interval 0.82 to 1.12.
Gene-disease validity (ClinGen):
ClinGen rates the evidence that ECHS1 causes each of these diseases.
Leigh syndrome (autosomal recessive): Definitive. A progressive neurological disease defined by specific neuropathological features associating brainstem and basal ganglia lesions.
mitochondrial short-chain Enoyl-Coa hydratase 1 deficiency (autosomal recessive): Definitive.
Homologues: Orthologues: macaque ECHS1 (96% identical), dog ECHS1 (88% identical), mouse Echs1 (88% identical), rat Echs1 (87% identical), guinea pig ECHS1 (84% identical), rabbit ECHS1 (84% identical), pig ECHS1 (83% identical), chimpanzee ECHS1 (80% identical), zebrafish echs1 (70% identical), tropical clawed frog echs1 (70% identical), Caenorhabditis elegans ech-6 (56% identical), Drosophila melanogaster Echs1 (56% identical), and 1 more. Paralogues in human: ECHDC2 (33% identical), AUH (32% identical), ECHDC3 (30% identical), HIBCH (30% identical), CDYL (29% identical), CDYL2 (26% identical), ECH1 (26% identical), CDY1B (26% identical), CDY2A (26% identical), CDY2B (26% identical), CDY1 (25% identical), ECHDC1 (22% identical), and 1 more.
Diseases named in the same sentence as ECHS1 in open-access papers:
ECHS1 is named in the same sentence as 96 diseases in open-access papers, as found by Europe PMC text mining. Sharing a sentence is not in itself a finding about the gene and the disease. The quoted sentences say what the papers report.
Leigh syndrome (21 papers, 2015 to 2026). "Enoyl-CoA hydratase short-chain 1 (ECHS1) variants are among the most common causes of Leigh syndrome." (PMID 41769478, 2026). "ECHS1 deficiency (ECHS1D) commonly present with Leigh Syndrome, a severe neurodegenerative condition characterized by bilateral symmetric brain lesions, developmental delay, dystonia, metabolic acidosis and cardiomyopathy." (PMID 40149952, 2025). "Loss of ECHS1 function results in widespread neuronal apoptosis, which correlates with the pathological hallmarks of Leigh syndrome and ethylmalonic encephalopathy." (PMID 40804397, 2025). "Subsequent research identified mutations in the ECHS1 gene as a causative factor in various mitochondrial disorders, most notably Leigh syndrome." (PMID 40804397, 2025). "Urine cysteine/cysteamine conjugates with acrylyl-CoA are routinely used to diagnose Leigh syndrome where the conversion of acrylyl-CoA to 3-hydroxypropionyl-CoA is inhibited due to a deficiency in the short chain enoyl-CoA hydratase (ECHS1) activity." (PMID 35931118, 2022). "The SCEC conjugate has also been proposed as a biomarker for Leigh syndrome suggesting a deficiency in ECHS1 activity due to acrylyl-CoA accumulation." (PMID 35931118, 2022). "Short-chain enoyl-CoA hydratase (ECHS1) is involved in amino and fatty acid catabolism in mitochondria and its deficiency results in Leigh syndrome or exercise-induced dystonia." (PMID 35681821, 2022). "ECHS1 deficiency (OMIM 602292) causes Leigh syndrome and/or exercise-induced dystonia in milder forms and more than 60 cases have been reported." (PMID 34667719, 2021). "Patients with ECHS1 deficiency commonly manifest with Leigh syndrome, also known as subacute necrotizing encephalomyelopathy, which is usually associated with defects in oxidative phosphorylation." (PMID 32316520, 2020). "Our study enriched the mutation spectrum of the ECHS1 gene, confirmed the phenotypic presentations, and highlighted the importance of the valine catabolic pathway in Leigh syndrome." (PMID 32677908, 2020). "Recessive ECHS1 variants induce leukoencephalopathy, changes in the basal ganglia consistent with Leigh syndrome, hypotonia, global developmental delay, cardiomyopathy, and early death." (PMID 33426505, 2020). "Deficiency of ECHS1 protein disrupts mitochondrial functions and may lead to brain pathology, such as Leigh syndrome characterized by psychomotor regression, and has been linked to psychiatric symptoms." (PMID 35999196, 2022). "However, patients with deficiencies in the FAO enzyme ECHS1 are typically diagnosed with Leigh syndrome, which is normally associated with OXPHOS dysfunction." (PMID 36064416, 2022). "Patients with ECHS1 deficiency typically present with developmental delay and neurological deterioration from the neonatal or early infantile period, presenting features of Leigh syndrome with basal ganglia lesions and lactic acidemia." (PMID 34667719, 2021). "The patient was diagnosed with Leigh syndrome secondary to possible ECHS1 deficiency." (PMID 34667719, 2021). "23DH2MB abnormalities were also identified in a few Leigh syndrome patients with ECHS1 mutations." (PMID 33762937, 2021). "The patient was diagnosed with Leigh syndrome due to ECHS1 deficiency." (PMID 34667719, 2021). "Pharmacological manipulation of mTOR might alleviate the metabolic effects of ECHS1‐deficiency paralleling the results obtained in other genetic forms of mitochondrial‐related neurodegeneration, including Leigh Syndrome." (PMID 32329585, 2020). "In profile 41, short-chain enoyl-CoA hydratase, short chain 1 (ECHS1) was involved in amino and fatty acid catabolism in mitochondria, mainly catalyzing the hydration step of fatty acids, and its deficiency can lead to Leigh syndrome or exercise-induced dystonia." (PMID 37808112, 2023).
Leigh syndrome (continued). "Indeed, very recently, ECHS1 mutations were reported in two siblings with Leigh disease and remarkable clinical and biochemical similarities to HIBCH deficiency, with most prominent elevations of methacrylate and acrylate metabolites indicating deficiency of valine oxidation." (PMID 26000322, 2015). "Additionally, we found ECHS1 to be an intriguing candidate because it is the only gene involved in fatty acid oxidation (FAO) whose mutations in patients manifest clinical characteristics compatible with Leigh syndrome (LS), a disease commonly associated with OXPHOS defects." (PMID 40301572, 2025). "Patients deficient in ECHS1 (ECHS1 deficiency, ECHS1D) present as a specific subset of Leigh Syndrome, with developmental delay, dystonia and numerous neurological defects." (PMID 36293464, 2022). "Short-chain enoyl-CoA hydratase (ECHS1) is involved in amino acid and fatty acid catabolism in mitochondria and its deficiency causes Leigh syndrome or exercise-induced dystonia." (PMID 34667719, 2021). "Inherited mutations in the ECHS1 and HIBCH enzymes of the valine catabolic pathway lead to the development of Leigh syndrome, a neurological disorder characterized by mitochondrial defects." (PMID 34961760, 2021). "Unlike the other FAO enzymes, mutations in ECHS1 result in clinical presentations characterized by Leigh syndrome." (PMID 40301572, 2025).
cardiomyopathy (9 papers, 2015 to 2025). A disease of the heart muscle or myocardium proper. "In human newborns or children, mutations in the ECHS1 (Short-chain enoyl-CoA-hydratase) gene lead to cardiomyopathies, such as hypertrophic cardiomyopathy." (PMID 39606030, 2024). "The symptoms of ECHS-1 deficiency include acute encephalopathy (Leigh or Leigh-like on MRI), deafness, dystonia, optic atrophy, cardiomyopathy, and lactic acidosis." (PMID 37297992, 2023). "Mitochondrial diseases resulting from ECHS1 mutations are often characterised by encephalopathy, deafness, epilepsy, optic atrophy, cardiomyopathy, dystonia, and lactic acidosis." (PMID 32354323, 2020). "Data showed that the relative strength of association between the ECHS1 gene and cardiomyopathy was -log10(p-value) = 1.62423." (PMID 30541556, 2018). "A dataset containing 2756 genes/proteins associated with cardiomyopathies from the curated CTD (Comparative Toxicogenomics Database) Gene-Disease Associations dataset was used to evaluate the link between the ECHS1 gene and cardiomyopathy." (PMID 30541556, 2018). "Moreover, p300-driven H3K9ac also appears to be involved in cardiomyopathy associated with loss-of-function mutations of Short-chain enoyl-CoA hydratase (ECHS1)—a key mitochondrial enzyme for fatty acid β-oxidation." (PMID 36766773, 2023). "Taken together, our findings identified ECHS1 mutations as a cause of a new clinical entity characterized by an early onset, very severe (Leigh-like) mitochondrial encephalopathy with deafness, epilepsy, optic atrophy, and cardiomyopathy." (PMID 26000322, 2015). "Here, we report 10 unrelated individuals, identified by exome sequencing, who carry compound heterozygous or homozygous ECHS1 mutations and present with a combination of (Leigh-like) mitochondrial encephalopathy, deafness, epilepsy, optic nerve atrophy, and cardiomyopathy." (PMID 26000322, 2015). "Among the diseases, the ECHS1 gene contributes are cardiovascular diseases, cardiomyopathies, and heart failure." (PMID 30541556, 2018).
breast carcinoma (7 papers, 2019 to 2025). "Furthermore, our findings reveal that the expression of ECHS1 is linked to various cancers, including colorectal cancer, hepatocellular carcinoma, and breast cancer, through its effects on metabolism and cell signaling pathways." (PMID 39328412, 2024). "When miR-548-3p was increased, it slowed down the growth of breast cancer cells by reducing ECHS1 expression." (PMID 40396180, 2025). "In a study on breast cancer, the expression of Enoyl-CoA hydratase (ECHS1) was reported to be higher in breast cancer cells and tissues." (PMID 40396180, 2025). "In colorectal cancer 7, 8, hepatocellular carcinoma 9, 10, and breast cancer 11, the expression of ECHS1 is markedly elevated than the adjacent healthy tissues and can promote tumor cell growth and migration and chemotherapy resistance." (PMID 38169583, 2024). "For instance, in colorectal cancer 7, 8, hepatocellular carcinoma 9, 10, and breast cancer 11, ECHS1 expression is markedly upregulated and promotes tumor cells' ability to proliferate, migrate, and chemotherapy resistance." (PMID 38169583, 2024). "For instance, miR-548 was found to inhibit the growth of breast cancer cells by downregulating ECHS1, and the downregulation of miR-548an was reported to promote pancreatic tumorigenesis." (PMID 31327761, 2019).
lactic acidosis (7 papers, 2015 to 2025). Metabolic acidosis characterized by the accumulation of lactate in the body. "HIBCH deficiency or loss of the short-chain enoyl-CoA hydratase (ECHS1) activity generates excess methacrylyl-CoA, which is a causing factor for metabolic diseases such as liver dysfunction, impaired ATP production, and lactic acidosis." (PMID 41226219, 2025). "ECHS1 mutation or ECHS1 deficiency is known as a primary cause leading to lactic acidosis in neonate that maybe related to mitochondrial fatty acid oxidation disorder." (PMID 34748517, 2021). "A recent Spanish study demonstrated that HIBCH deficiency was completely correlated to LSS, and ECHS1 deficiency displayed LSS, but also fatal neonatal lactic acidosis and paroxysmal dystonia." (PMID 37628588, 2023). "In contrast, milder cases of ECHS1 deficiency do not show reduced PDC activity or lactic acidosis." (PMID 36064416, 2022).
developmental delay (6 papers, 2020 to 2025). "This disorder results from missense loss-of-function mutations in the ECHS1 gene that results in severe developmental delays, encephalopathy, hypotonia and early death." (PMID 41426433, 2025). "This disorder results from missense loss-of-function mutations in the ECHS1 gene that result in severe developmental delays, encephalopathy, hypotonia, and early death." (PMID 38915588, 2024). "The patient presented early in infancy with clinical signs and laboratory findings typical of SCEH deficiency including severe developmental delay, abnormal brain MRI, elevation of urinary 3‐methylglutaconic acid, and bi‐allelic mutations in the ECHS1 gene." (PMID 33931985, 2021). "Mutations in ECHS1 cause rare autosomal recessive disorders mainly presenting with developmental delay, dystonia, feeding difficulties, and abnormal neuroimaging with bilateral basal ganglia involvement." (PMID 34256807, 2021). "Polymorphic clinical features, such as severe developmental delay or regression, feeding difficulties, faltering growth, profound irritability, central hypotonia, seizures, visual impairment, and cardiomyopathy, were previously reported in cases with ECHS1 deficiency." (PMID 35206276, 2022).
Mitochondrial encephalopathy (6 papers, 2015 to 2022). "ECHS1 deficiency leads to mitochondrial encephalopathy, as shown by delayed motor and cognitive development and abnormal brain MRI signals in the nucleus accumbens and caudate nucleus." (PMID 36188600, 2022). "Biallelic mutations in ECHS1, encoding the mitochondrial enoyl‐CoA hydratase, have been associated with mitochondrial encephalopathies with basal ganglia involvement." (PMID 32329585, 2020). "Our findings are the first to report a mitochondrial encephalopathy infant carrying two novel ECHS1 variants, c.414 + 5G > A and c.310C > G, which might be deleterious variants, function as pathogenicity markers for mitochondrial encephalopathy, and facilitate disease diagnosis." (PMID 32354323, 2020). "In this study, we report two novel heterogeneous variants, c.414 + 5G > A (in intron 3) and c.310C > G (in CDS), of ECHS1 in an infant with mitochondrial encephalopathy." (PMID 32354323, 2020). "Lack of ECHS1 leads to mitochondrial encephalopathy, and ECHS1 plays an important role in maintaining mitochondrial function." (PMID 35496302, 2022).
colorectal cancer (5 papers, 2021 to 2025). A primary or metastatic malignant neoplasm that affects the colon or rectum. "Previous studies have indicated that branched-chain amino acids (BCAAs) in colorectal cancer enhance the acetylation of K204 in ECHS1, thereby impairing its ability to bind to enoyl-CoA and diminishing its catalytic activity." (PMID 40906076, 2025). "In this study, through an LC–MS assay, LIM and SH3 protein 1 (LASP1) was identified as a sphingolipid-metabolism-involved protein, and short-chain enoyl-CoA hydratase (ECHS1) was identified as a new LASP1-interacting protein through a protein assay in colorectal cancer (CRC)." (PMID 34615856, 2021).
Dystonia (5 papers, 2020 to 2023). An abnormally increased muscular tone that causes fixed abnormal postures. "We described two siblings with ECHS1‐deficiency associated with a novel dystonia‐ataxia syndrome allowing survival into adulthood." (PMID 32329585, 2020).
Encephalopathy (4 papers, 2015 to 2025). Encephalopathy is a term that means brain disease, damage, or malfunction. "In this study, we reported two novel ECHS1 variants and provided experimental evidence that attests to the functional significance of these variants and their association with severe encephalopathy." (PMID 32354323, 2020).
Hepatic steatosis (4 papers, 2011 to 2024). Steatosis is a term used to denote lipid accumulation within hepatocytes. "In rats, down-regulation of ECHS1 has been identified as a contributing factor in high-fat diet induced hepatic steatosis, causing decreased mitochondrial fatty acid β-oxidation, a finding that was validated in patients with simple steatosis." (PMID 21339799, 2011). "CAT and ECHS1 were reported to be important enzymes in the fat metabolism of fatty liver disease." (PMID 38674414, 2024). "Similarly, we also observed the attenuated hepatic steatosis and the decrease of SREBP1c, Pparγ, Scd1 and Cd36 involved in lipogenesis and lipid uptake, and increase of Cpt1, Acat and Echs1 involved in fatty acid oxidation in the liver of mice fed HFD and hemin." (PMID 28933767, 2017). "Increased IL-17 elevated the transcription of SREBP-1c and ChREBP but suppressed ECHS1 and PPAR-α; anti-IL-17 antibody improved hepatic steatosis by suppressing interleukin-17-related fatty acid metabolism." (PMID 24396389, 2013).
hepatocellular carcinoma (4 papers, 2017 to 2024). A malignant tumor that arises from hepatocytes. "SS binds with enoyl-coA hydratase short chain 1 (ECHS1), which is located in the mitochondrial matrix, acts on the fatty acid beta-oxidation pathway, and reduces the ECHS1 expression in hepatoma cells." (PMID 32033216, 2020). "Moreover, exposure to glucose dose-dependently decreased endogenous ECHS1 levels, but not those of enzymes functioning either upstream or downstream of ECHS1 in human liver carcinoma HepG2 cells." (PMID 28878358, 2017).
gastric cancer (3 papers, 2021 to 2024). A primary or metastatic malignant neoplasm involving the stomach. "Tryptophan Metabolism-associated Genes (TMGs), such as ECHS1 and ALDH2, are crucial in cancer progression through immunosuppressive mechanisms, particularly in Gastric Cancer (GC)." (PMID 39328412, 2024). "Additionally, in the human gastric cancer cell lines, the protein levels of ECHS1 were significantly higher than those in nonneoplastic gastric epithelial mucosa cells." (PMID 34615856, 2021).
Acute encephalopathy (2 papers, 2023 to 2026). "A five-year-old boy with ECHS1 deficiency initially presented with acute encephalopathy during the neonatal period." (PMID 41769478, 2026). "ECHS-1 deficiency is a mitochondrial disease that causes acute encephalopathy, and its recognition has increased in recent years." (PMID 37297992, 2023).